GPR65 (G protein-coupled receptor 65)
Diseases named in the same sentence as GPR65 in open-access papers (continued):
Sharing a sentence is not in itself a finding about the gene and the disease.
tumor (continued). "We therefore quantified tumor and CAR T-cell numbers in mice with no tumor or m.CR or GPR65 KO tumors 4 days after CAR T treatment." (PMID 39998425, 2025). "However, macrophage-depleted mice with either m.CR or GPR65 KO tumors responded equivalently and fully to CAR T-cell therapy; complete remission with no tumor relapse was seen even after the depletion regimen was ended." (PMID 39998425, 2025). "These paradoxical effects may be highly tumour- and TME-phenotype-specific, due to the multiple roles GPR65 signalling plays across different immune and non-immune cell compartments." (PMID 41375084, 2025).
cancer (26 papers, 2013 to 2025). A tumor composed of atypical neoplastic, often pleomorphic cells that invade other tissues. "Some studies report that a loss or reduction in GPR65 activity can foster resistance to apoptosis, facilitate immune escape, and even increase the risk of secondary cancers." (PMID 41375084, 2025). "Our GPR65 genotype stratification analyses revealed an association between homozygosity for the I231L GPR65 loss of function variant (rs3742704) and an improved survival across all TCGA cancer types." (PMID 39483470, 2024). "However, it is important to note that these observations are context-dependent; GPR65 knockout has also been associated with treatment resistance in haemato-oncology treatment resistance and increased secondary cancer." (PMID 41375084, 2025). "GPR65 (also known as T-cell death-associated gene 8, TDAG8) is an extracellular pH-sensing G protein-coupled receptor involved in the regulation of cancer cell metastasis and proliferation, immune cell function, inflammation and angiogenesis, etc.." (PMID 40519919, 2025). "Blocking GPR65 has been shown in early laboratory studies to restore the ability of immune cells to recognise and attack cancer." (PMID 41375084, 2025). "Next, we queried public scRNAseq datasets to determine the relative expression levels of GPR65 mRNA in immune cells of the TME across multiple cancer indications." (PMID 39483470, 2024). "In this study, we explored the potential of GPR65 as a target for cancer immunotherapy and its relevance to human T-cell biology." (PMID 39483470, 2024). "We reasoned that stratifying cancer patients based on their GPR65 genotype may provide insights into the role of GPR65 in cancer immunity and we assessed patient overall survival (OS) as a function of GPR65 risk allele rs3742704 presence from the pan-cancer TCGA dataset." (PMID 39483470, 2024). "Since H+ concentrations are locally increased in several solid tumours, it is conceivable that GPR65 acts to dampen the anti-cancer activity of T-cells present in the TME." (PMID 39483470, 2024). "Our findings provide several lines of evidence in support of a suppressive role for GPR65 in T-cell responses against cancer." (PMID 39483470, 2024). "Surprisingly, our study is completely different from other studies, where the higher the expression of GPR65, the worse the malignancy and prognosis of cancer." (PMID 38218960, 2024). "GPR65 expression promotes cancer development in several solid cancers." (PMID 39336742, 2024). "We report in silico investigations suggesting that GPR65 inhibition could be beneficial for cancer immunotherapy and that human T-cell functions are downmodulated by GPR65." (PMID 39483470, 2024). "Therefore, further Pearson analysis was conducted to investigate the correlation between GPR65 and common cancer immune checkpoint inhibitors, such as CD200R1, CD47, HAVCR2, TIGIT, CTLA4, LAG3, and PD1." (PMID 38218960, 2024). "An upcoming clinical trial in cancer with the small molecule GPR65 inhibitor PTT-4256 was recently announced and may provide clues as to the therapeutic potential of GPR65 modulation." (PMID 39483470, 2024). "To consolidate these findings, we explored BioTuring resource, a second pan-Cancer transcriptomic single cell database including ~98M annotated cells in over 1,600 studies and confirmed that GPR65 gene is frequently expressed by the previously identified cell populations." (PMID 39483470, 2024). "However, the divergent directions of the accumulated evidences suggest that the role of GPR65 in cancer may greatly depend on each specific context." (PMID 33113952, 2020). "T-cell function is also impaired via GPR65 signalling, with experimental data demonstrating that GPR65 activity significantly inhibited antigen-specific, CD8+ T-cell cytotoxic activity against target cancer cells." (PMID 41375084, 2025).
cancer (continued). "PTT-4256, a first-in-class, oral, small-molecule GPR65 inhibitor, is currently under evaluation in the Phase I/II RAISIC-1 trial (Relief of Acidic Immune Suppression in Cancer; NCT06634849)." (PMID 41375084, 2025). "In another study, GPR65 and its downstream PKA pathway were engaged in the perception of cancer pain in rats." (PMID 40519919, 2025). "Herein, we review the current research progress pertaining to these proton-sensing GPCRs, including GPR4, GPR65 (TDAG8), and GPR68 (OGR1), in inflammation and cancer." (PMID 39336742, 2024). "Collectively, these results consolidate previous research reporting that GPR65 may be a therapeutically relevant target in IO and expand the range of its immune-suppressive activity to T-cells, which represent a major effector cell population in cancer immunotherapy." (PMID 39483470, 2024). "A decrease in extracellular pH promotes growth, migration, invasion, and metastasis of cancer cells in an acidic environment via GPR4, GPR65 (TDAG8), GPR68 (OGR1), and GPR132 (G2A), which are pH-sensing G protein-coupled receptors (GPCRs)." (PMID 32998265, 2020). "Recent studies show that the pH-sensing GPCRs, including GPR4, GPR65 (TDAG8), GPR68 (OGR1), and GPR132 (G2A), regulate cancer cell metastasis and proliferation, immune cell function, inflammation, and blood vessel formation." (PMID 24367336, 2013). "However, our results showed that GPR65 expression was instead reduced in LUAD patients, which seemed to be inconsistent with the expression results in most cancer types." (PMID 40519919, 2025). "Single cell transcriptomic comparisons between T-cells isolated from non-tumoural and tumoural gastric or lung tissues showed similar levels of GPR65 mRNA, indicating that GPR65 expression does not seem to be increased at cancer sites." (PMID 39483470, 2024). "Finally, we extracted the top 20 in-degree and top 20 out-degree genes as the hub nodes of each cancer and identified six co-owned immune feature genes (CD48, GPR65, C3AR1, CD2, CD3E and ARHGAP9) in these cancers." (PMID 35069897, 2022). "Although some pharmacological modulators of GPR65 have been described, their role in the cancer context has not been analyzed." (PMID 33113952, 2020). "How GPR65 activation by extracellular acidosis promotes cancer cell survival has not been well defined." (PMID 25984552, 2014). "GPR65 has also been linked to intratumoral exhausted CD8+ T cells, which suggests that developing GPR65 inhibitors or negative allosteric modulators may be clinically relevant in cancer immunotherapy." (PMID 39028811, 2024).
hematologic malignancies (5 papers, 2016 to 2025). "Our findings in this study suggest that potentiation of the TDAG8 (GPR65) receptor pathway may be exploited as a potential therapeutic approach for the treatment of hematological malignancies." (PMID 29017562, 2017).
infection (4 papers, 2021 to 2023). The state of being infected such as from the introduction of a foreign agent such as serum, vaccine, antigenic substance or organism. "Upregulation of G protein-coupled receptor 65 (GPR65) persisted until day 7 post-infection, but only in the subset of cells that divided many times." (PMID 37111397, 2023). "Genes uniquely triggered by M. riyadhense infection compared with other mycobacteria included Cd22, Gpr65, Adh7 and TrnT; however, no functional categories were statistically enriched from this category of genes." (PMID 34396095, 2021).
blood cancer (3 papers, 2017 to 2024). "These few reports demonstrate that GPR65 can promote and inhibit blood cancer progression, which is dependent on cell type and context." (PMID 39336742, 2024). "Overall, this study confirms the notion that GPR65 gene expression provides a selective pressure against blood cancer cells." (PMID 39336742, 2024). "One comprehensive analysis revealed that GPR65 gene expression is reduced in the majority of blood cancers in comparison to normal immune cells or tissue." (PMID 39336742, 2024). "The outcome that precipitated from restoring GPR65 gene expression clearly confirmed that it inhibits blood cancer progression." (PMID 39336742, 2024). "The role of GPR65 in blood cancer progression is less clear." (PMID 39336742, 2024). "However, GPR65 function has not been adequately investigated in blood cancers." (PMID 39336742, 2024).
inflammation (3 papers, 2023). Aberrant reaction of the microcirculation characterized by movement of fluid and leukocytes from the blood into extravascular tissues. "Given the evidences that macrophage-enriched GPR65 was increased in HMs from the fibrotic livers and Gpr65 depletion ameliorated CCl4- and BDL-induced hepatic inflammation in vivo, we investigated the role of GPR65 on the polarization of macrophage in vitro." (PMID 38001521, 2023).
cardiovascular diseases (1 paper, 2018). "Interestingly, we were able to determine that GPR65 is associated with cardiovascular diseases." (PMID 29666662, 2018).
hematological cancers (1 paper, 2024). "Among these GPCRs, GPR85, GPR65, and GPR183 have varying numbers ofstudies in the field of hematological cancers and pediatric ALL." (PMID 39698279, 2024).
intestinal diseases (1 paper, 2021). "Recently, the expression of GPR65 was found to be closely associated with intestinal diseases." (PMID 34485279, 2021).
GPR65 also shares sentences with these, for which no sentence is quoted: colorectal cancer (6 papers); melanoma (4); asthma (3); autoimmune disease (3); acute myeloid leukemia (2); Anxiety (2); brain ischemia (2); breast carcinoma (2); cerebral infarction (2); diffuse large B-cell lymphoma (2); follicular lymphoma (2); globoid cell leukodystrophy (2); neurodegenerative disease (2); renal cell carcinoma (2); squamous cell carcinoma (2); Stroke (2); Alzheimer disease (1); ankylosing spondylitis (1); Anorexia (1); atherosclerosis (1); bacterial infection (1); basal cell carcinoma (1); bone marrow disease (1); brain tumor (1); Burkitt lymphoma (1); Cerebral ischemia (1); Cirrhosis (1); diabetes (1); eosinophilia (1); extranodal marginal zone B-cell lymphoma (1).
A further 26 diseases each share a sentence with GPR65 in 1 paper.